HOXA11 (homeobox A11)
Diseases named in the same sentence as HOXA11 in open-access papers (continued):
Sharing a sentence is not in itself a finding about the gene and the disease.
lung adenocarcinoma (7 papers, 2017 to 2022). A carcinoma that arises from the lung and is characterized by the presence of malignant glandular epithelial cells. "On the other hand, studies showed that HOXA11 was significantly lower in cisplatin-resistant lung adenocarcinoma cell line." (PMID 35349479, 2022). "We found that HOXA3 was low expressed in lung adenocarcinoma and had a protective effect on the prognosis of lung cancer patients; whereas HOXA11 and HOXA13 play oncogenic roles in lung adenocarcinoma 14-16." (PMID 35370463, 2022). "HOXA11 was significantly downregulated in cisplatin-resistant lung adenocarcinoma cell lines compared with parent cell lines, and in vitro experiments showed that overexpression of HOXA11 increased cisplatin sensitivity by inhibiting Akt/β-catenin signaling." (PMID 32296636, 2020). "In addition, in lung adenocarcinoma, HOXA11 hypermethylation seems to be related to cisplatin-resistance and to Akt/β-catenin signaling activation, which occurs without interfering with the methylation status of HOXA11 antisense (HOXA11AS)." (PMID 32635388, 2020). "HOXA10, HOXA11, and HOXA13 might be useful targets to further mine the molecular pathogenesis of HOXA11 in early-stage lung adenocarcinoma." (PMID 29914539, 2018).
glioblastoma (6 papers, 2016 to 2024). The most malignant astrocytic tumor (WHO grade IV). "In glioblastoma, overexpression of HOXA11 confers a tumor suppressive effect, reduces treatment resistance and contributes to a favorable prognosis." (PMID 32296636, 2020). "In glioblastoma, the decreased level of HOXA11 was confirmed as a significant marker of poorer prognosis." (PMID 29914539, 2018). "Interestingly, a recent publication suggested that HOXA11 expression correlated with glioblastoma patient treatment responses and prognosis." (PMID 27855695, 2016). "HOXA-11 was found hypermethylated in HCC and also in lung, glioblastoma, or endometrial carcinoma." (PMID 39305372, 2024).
leukemia (6 papers, 2016 to 2022). A malignant (clonal) hematologic disorder, involving hematopoietic stem cells and characterized by the presence of primitive or atypical myeloid or lymphoid cells in the bone marrow and the blood. "Similar to HOXA9, HOXA11 has been implicated in leukemia development, exemplified by a patient with juvenile myelomonocytic leukemia (JMML) carrying a NUP98-HOXA11 fusion gene." (PMID 31426381, 2019). "Together, this demonstrates unique dependency on a subset of the Hoxa cluster (Hoxa7, Hoxa9, Hoxa10, and Hoxa11) genes for maintenance of MA9 leukemia." (PMID 31861091, 2019). "Compared to levels in Hoxa9/Meis1 leukemias, endogenous Hoxa9 and Hoxa10 were considerably elevated in SQSTM1-NUP214 leukemias, whereas the levels of Hoxa3, Hoxa5, Hoxa7, Hoxa11 and Meis1 were comparable in Hoxa9/Meis1 and SQSTM1-NUP214 leukemias." (PMID 32343715, 2020).
renal cell carcinoma (6 papers, 2017 to 2022). "HOXA11 DNA methylation has already been identified as a potential biomarker in several cancers such as renal cell carcinoma, ovarian and cervical cancer, endometrial adenocarcinoma and non-small cell lung cancer." (PMID 35885590, 2022). "HOXA11 has been identified as a novel tumor suppressor in renal cell carcinoma, which inhibits cell proliferation, migration, and invasion, while inducing apoptosis." (PMID 33514011, 2021). "Collectively, our data identifies HOXA11 as a functional tumor suppressor which is frequently methylated in renal cell carcinoma." (PMID 28423531, 2017). "In this study, we investigated the expression, epigenetic changes and the function of HOXA11 in human renal cell carcinoma (RCC)." (PMID 28423531, 2017). "Moreover, HOXA11 regulated RCC cells apoptosis by inhibiting Wnt signaling in renal cell carcinoma, and its function was regarded as a tumor suppressor in RCC." (PMID 35342423, 2022). "However, the epigenetic alteration and function of HOXA11 in human renal cell carcinoma has not been explained." (PMID 28423531, 2017). "Epigenetic inactivation of HOXA11, a putative tumor suppressor, is frequently observed in a number of solid tumors, but has not been described in RCC (renal cell carcinoma)." (PMID 28423531, 2017).
endometrial polyp (5 papers, 2012 to 2025). A benign nodular lesion protruding above the surface of the endometrium. "HOXA10 and HOXA11 are downregulated in endometrial polyps, which may provide a molecular basis for reducing the pregnancy rate." (PMID 36246905, 2022). "Expression of HOXA10 and HOXA11 are shown to be decreased in endometrial polyps, which may provide a molecular basis for the decrease in pregnancy rates." (PMID 33079974, 2020). "Endometrial polyp-affected uteri showed a substantial decline in HOXA10 and HOXA11 messenger RNA levels compared to the controls, which may indicate decreased endometrial receptivity and impede implantation." (PMID 39941173, 2025).
glioma (5 papers, 2011 to 2023). A benign or malignant brain and spinal cord tumor that arises from glial cells (astrocytes, oligodendrocytes, ependymal cells). "Accordingly, HOXA9 and HOXA11 expression also increased from lower-grade glioma to high-grade glioma." (PMID 26356815, 2015). "Furthermore, antisense RNA of HOXA3 and HOXA11 have also shown prognostic values in glioma." (PMID 37351805, 2023). "By western-blot analysis, HOXA9, HOXA11, and HOXA13 were dramatically up-regulated in GBM, and HOXA10 merely showed a slight increase in high-grade glioma." (PMID 26356815, 2015). "In the present study, we first analyzed the expression of HOXA9, HOXA10, HOXA11, and HOXA13 protein in glioma tissues; we then further analyzed the expression of HOXA9, HOXA10, HOXA11, HOXA13, and HOTTIP mRNA in the same samples." (PMID 26356815, 2015). "In order to explore the role of the 5′ HOXA genes in gliomas, we first measured the expression of HOXA9, HOXA10, HOXA11, and HOXA13 protein in 66 gliomas specimens of different grades." (PMID 26356815, 2015). "The highest correlation value for the HOXA11 gene (r = 0.4) was not significant, suggesting that chromosome 7 gain contributes but is not the main driving force of HOXA gene upregulation in IDHwt glioma samples." (PMID 33720519, 2021).
pancreatic cancer (5 papers, 2015 to 2024). "Pioneering work in pancreatic cancer demonstrated the HOTTIP-targeted regulation of HOXA11 expression." (PMID 29415429, 2018). "The siRNA-mediated knockdown of HOTTIP resulted in a clear reduction of several HOX genes, particularly HOXA11 expression in Panc1 pancreatic cancer cells." (PMID 29415429, 2018). "Previous studies indicated that HOXA10 and HOXA11 regulate expression of MMP-3 and MMP-2, respectively, and both MMPs contribute to migration/invasion of pancreatic cancer cells." (PMID 25912306, 2015). "In pancreatic cancer cells, HOTTIP regulates HOXA10, HOXB2, HOXA11, HOXA9 and HOXA1, but not HOXA13." (PMID 30819158, 2019). "However, another study in pancreatic cancer cells demonstrated that HOTTIP did not modulate HOXA13 expression, but did regulate the expression of other HOX genes such as HOXA1, HOXA9, HOXA10, HOXA11 and HOXB2." (PMID 28938659, 2017).
adenomyosis (4 papers, 2013 to 2025). The growth of endometrial tissue inside the muscular wall of the uterine corpus. "Similarly, adenomyosis alters HOXA11-regulated ECM remodeling and β3-integrin expression, impairing embryo attachment." (PMID 40305321, 2025). "Thus, the downregulation of HOXA10 and HOXA11 expression by HIF-2α overexpression may be involved in the pathogenesis of adenomyosis in mice." (PMID 36834456, 2023). "Additionally, studies with experimental animal models for adenomyosis revealed that the expression of hypoxia-inducible factor-2α (HIF-2α) in the adenomyosis group was higher than in the control group and that HIF-2α antagonists increased the mRNA and protein expression of HOXA10 and HOXA11." (PMID 36834456, 2023).
colon cancer (4 papers, 2009 to 2023). "COBRA experimental results confirmed a different methylation state at the HOXA11 promoter among the colon cancer cell lines." (PMID 28751909, 2017). "Chr7:27225772 at the HOXA11 promoter and chr17:63554340 at the AXIN2 promoter were also detected as colon cancer-specific cDMCs." (PMID 28751909, 2017). "For example, the HOXA11 cDMC was either unmethylated (HT-29, Lovo, SNU61, SNU-C1, and SNU-C4) or heavily methylated (HCT116, SNU1033, SNU188, SNU407, and SW620) in the colon cancer cell lines." (PMID 28751909, 2017).
endometrial adenocarcinoma (4 papers, 2013 to 2022). "Several studies have revealed that HOXA11 promoter methylation is related to different tumors, such as endometrial adenocarcinoma, ovarian cancer and glioblastoma." (PMID 28717185, 2017).
leiomyoma (4 papers, 2013 to 2025). A well-circumscribed benign smooth muscle neoplasm characterized by the presence of spindle cells with cigar-shaped nuclei, interlacing fascicles, and a whorled pattern. "Its proximal associated gene HOXA11 was decreased in endometrium of patients with submucosal and intramural leiomyomas." (PMID 35641855, 2022). "Our data indicated increased expression of RP1-170O19.14 and its proximal gene HOXA11 in leiomyomas." (PMID 35641855, 2022). "Our findings implicate SE-lncRNAs in leiomyoma tumorigenesis and progression through the regulation of potential downstream target genes which are in close proximity to their transcription sites (e.g., SOCS2, CBX4, HOXA11, PRL, SPARC, and EGFLAM)." (PMID 35641855, 2022). "To determine whether myomectomy would reverse HOXA11 and HOXA10 expression, we evaluated the transcript levels of these genes in the endometrium of patients with intramural fibroid before and after myomectomy." (PMID 24639724, 2013). "This study provides evidence that removal of intramural leiomyomas not affecting the expression pattern of HOXA10 and HOXA11 endometrial genes." (PMID 24639724, 2013).
non-small cell lung carcinoma (4 papers, 2013 to 2024). A group of at least three distinct histological types of lung cancer, including non-small cell squamous cell carcinoma, adenocarcinoma, and large cell carcinoma. "The association of HOXA-AS2, HOXA11,HOTTIP, HOXA1, HOXA3 and HOXA4 expression with survival of non-small-cell lung cancer." (PMID 39121297, 2024). "This study was aimed at understanding the functional significance of HOXA11 hypermethylation in non-small cell lung cancer (NSCLC)." (PMID 24259349, 2013).
cervical cancer (2 papers, 2021 to 2022). A primary or metastatic malignant neoplasm involving the cervix. "Our results showed that the HOXA1 gene was upregulated, while the HOXA10 and HOXA11 were downregulated in cervical cancer." (PMID 34606634, 2021). "In summary, this study represented the expression status of HOXA members in cervical cancer and identified three differentially expressed HOXA genes (HOXA1, HOXA10, and HOXA11) with great discriminative ability in cervical cancer." (PMID 34606634, 2021). "The expression profile of HOXA family was presented by pheatmap of R software, the result showing significant differences in HOXA1, HOXA10, and HOXA11 expression between cervical cancer and normal controls." (PMID 34606634, 2021). "Our results demonstrated that the expression of HOXA1 was upregulated in cervical cancer (p value for HOXA1 = 0.0128), while HOXA10 and HOXA11 expression was downregulated in cervical cancer compared with the normal control (p value for HOXA10 = 0.0123, p value for HOXA11 = 8.045E‐5)." (PMID 34606634, 2021). "We also identified a significantly increased abundance of T helper 2 cells (Th2) and higher expression of PD‐L1 in cervical cancer patients with lower expression of HOXA10 and HOXA11." (PMID 34606634, 2021). "The expression of HOXA1 was significantly upregulated in cervical cancer compared to normal control, whereas HOXA10 and HOXA11 were downregulated in cervical cancer." (PMID 34606634, 2021). "In our study, higher expression of PD‐L1 was observed in cervical cancer patients with low‐HOXA10 and HOXA11 expression." (PMID 34606634, 2021). "Firstly, we compared the expression of HOXA members in cervical cancer than normal controls, and results showed only three HOXA members with statistical significance (HOXA1, HOXA10, and HOXA11)." (PMID 34606634, 2021). "Firstly, patients with cervical cancer were classified into two different group based on the cutoff value of HOXA1, HOXA10, and HOXA11 expression from ROC." (PMID 34606634, 2021). "Our results showed that among three differentially expressed HOXA genes (HOXA1, HOXA10, and HOXA11), HOXA1 was the only prognostic gene in cervical cancer." (PMID 34606634, 2021). "We identified three differentially expressed HOXA members in cervical cancer (upregulated HOXA1 and downregulated HOXA10 and HOXA11)." (PMID 34606634, 2021). "Pearson's correlation results showed that almost all assessed cg sites of HOXA1, HOXA10, and HOXA11 exhibited a negative correlation with expression in cervical cancer." (PMID 34606634, 2021). "Considering favorable efficacy in immune checkpoint inhibitors (especially PD‐1/PD‐L1 inhibitors) achieved in treating cervical cancer, our study also assessed the expression status of CTLA4, PD‐1, and PD‐L1 in cervical cancer patients grouped by different expression of HOXA1, HOXA10, and HOXA11." (PMID 34606634, 2021). "Subsequently, a significantly increased abundance of T helper 2 cells (Th2) and higher expression of PD‐L1 were observed in cervical cancer patients with lower expression of HOXA10 and HOXA11, indicative of the fact that HOXA10 and HOXA11 could be served as biomarkers of response to immunotherapy." (PMID 34606634, 2021).
colorectal cancer (2 papers, 2020 to 2022). A primary or metastatic malignant neoplasm that affects the colon or rectum. "Several overexpression and knockdown studies have shown that HOXA11 is involved in regulating the liver metastasis in colorectal cancer cell lines." (PMID 35885590, 2022).
endometrial carcinoma (2 papers, 2013 to 2017). A malignant tumor arising from the epithelium that lines the cavity of the uterine body. "Most previous studies acknowledge that abnormal epigenetic alterations of TSGs (e.g., PTEN, 14-3-3σ, MLH1, HOXA11) contribute to endometrial carcinoma." (PMID 23840707, 2013).
female infertility (2 papers, 2021 to 2025). Diminished or absent ability of a female to achieve conception. "Like HOXA10, HOXA11 expression plays animportant role in implantation and the down regulationof this gene leads to female infertility." (PMID 32347039, 2021).
multiple myeloma (2 papers, 2022 to 2023). "Additionally, MEG3 is downregulated in multiple myeloma where it acts as an endogenous competitive RNA with miR-181a, inhibiting tumor progression and possibly regulating HOXA11 by sponging miR-171a." (PMID 36869839, 2023).
adenocarcinoma in situ (1 paper, 2018). A lesion in which the normally situated glands are partially or completely replaced by atypical cells with malignant characteristics. "CpG islands in HOXA11 have been found to be hypermethylated in invasive NSCLC and adenocarcinoma in situ (AIS)." (PMID 29796116, 2018).
breast tumors (1 paper, 2017). "Hypermethylation of HOXA11 represented 119 out of 264 (45.08%) primary breast tumors surveyed, while only 6.82% of normal tissues were defined as HOXA11 hypermethylation." (PMID 28038461, 2017).
chronic endometritis (1 paper, 2024). A non-granulomatous or granulomatous chronic inflammation of the endometrium. "Therefore, in this study we attempted to demonstrate a possibleimpact of chronic endometritis on the expression of HOXA10 and HOXA11 in infertilewomen." (PMID 38801313, 2024).
cryptorchidism (1 paper, 2021). The failure of one or both testes of a male fetus to descend from the abdomen into the scrotum during the late part of pregnancy. "Numerous Hox family members have been associated with mammalian sexual development, including Hoxa11 which have been associated with cryptorchidism." (PMID 34015032, 2021).
dysplasia (1 paper, 2018). A usually neoplastic transformation of the cell, associated with altered architectural tissue patterns. "The HOXA11/HOXD11 genes are particularly intriguing candidates as potential upstream regulators of SHOX since their mutation in mice causes zeugopodal truncations similar to that of Langer mesomelic dysplasia patients." (PMID 30250174, 2018).
esophageal cancer (1 paper, 2021). A primary or metastatic malignant neoplasm involving the esophagus. "First, we removed lncRNAs with longer than 4000 nucleotides and then eliminated the molecules that have already been studied in esophageal cancer such as H19, SNHG6, LUCAT1, HOXA11." (PMID 34659577, 2021).
Ewing sarcoma (1 paper, 2014). A small round cell tumor that lacks morphologic, immunohistochemical, and electron microscopic evidence of neuroectodermal differentiation. "The methylation of these top four genes was confirmed to be common, occurring in 82.5% (GDF), 65% (OSM), 87.5% (APC) and 45% (HOXA11) of the Ewing’s sarcoma samples." (PMID 25202378, 2014). "Using a highly stringent selection criteria (a β difference of <0.5), four unique genes (GDF, OSM, APC and HOXA11) were selected that were the most significantly differentially-methylated genes in the Ewing’s sarcoma samples." (PMID 25202378, 2014). "Thus, four unique genes (GDF10, OSM, APC, and HOXA11) were selected that were the most significantly differentially methylated in the Ewing’s sarcoma samples." (PMID 25202378, 2014).
fibrosis (1 paper, 2024). the formation of excess fibrous connective tissue in an organ or tissue in a reparative or reactive process. "Thus, our data indicated that Egr1 is key molecules involved in the peritoneal mesothelial fibrosis promoted by HOXA11 over-expressed GC cells." (PMID 37989866, 2024).
gastric adenocarcinoma (1 paper, 2022). "DNA methylation of HOXA11 gene promoter is more frequent in gastric cancer tumor tissue than in healthy gastric mucosa and is associated with shorter postoperative survival in patients diagnosed with gastric adenocarcinoma." (PMID 35885590, 2022). "Only a few studies have investigated the role of HOXA11 in the carcinogenesis and progression of gastric adenocarcinoma." (PMID 35885590, 2022). "Our results suggest that the HOXA11 gene might be a prognostic molecular marker in patients with gastric adenocarcinoma." (PMID 35885590, 2022). "Our results suggest that the HOXA11 gene might be a potential prognostic molecular marker in patients with gastric adenocarcinoma." (PMID 35885590, 2022).
Insulin resistance (1 paper, 2023). Increased resistance towards insulin, that is, diminished effectiveness of insulin in reducing blood glucose levels. "In PCOS animals exhibiting insulin resistance, BBR improves endometrial receptivity via modulating the endometrial implantation genes (LPAR3, αvβ3, and HOXA11), although the exact mechanism is still under investigation." (PMID 36676074, 2023).